SLC35G5 (solute carrier family 35 member G5)
Synonyms: AMAC; AMAC1L2
Tractability: Antibody: UniProt predicts a signal peptide or a membrane-spanning region.
Gene: Protein-coding gene on chromosome 8 (11,331,012 to 11,332,360, forward strand). Ensembl gene ENSG00000177710.
Subcellular location: Membrane
Gene Ontology:
Molecular function: protein binding
Cellular component: membrane
Genetic constraint (gnomAD): Loss-of-function variants: 14 observed, 18.04 expected, observed/expected ratio (o/e) 0.78, 90% interval 0.51 to 1.21. The upper end of that interval is the gene's LOEUF score, 1.21, which puts it in group 5 of 6, group 1 being the genes least tolerant of losing a copy. Missense variants: 541 observed, 420.97 expected, observed/expected ratio (o/e) 1.29, 90% interval 1.2 to 1.38. Synonymous variants: 236 observed, 194.73 expected, observed/expected ratio (o/e) 1.21, 90% interval 1.09 to 1.35.
Homologues: Orthologues: macaque SLC35G6 (91% identical), dog SLC35G6 (88% identical), mouse Slc35g3 (82% identical), rat Slc35g3 (81% identical), Drosophila melanogaster CG5281 (14% identical). Paralogues in human: SLC35G4 (93% identical), SLC35G6 (93% identical), SLC35G3 (92% identical), SLC35G2 (28% identical), SLC35G1 (18% identical).
Diseases named in the same sentence as SLC35G5 in open-access papers:
SLC35G5 is named in the same sentence as 5 diseases in open-access papers, as found by Europe PMC text mining. Sharing a sentence is not in itself a finding about the gene and the disease. The quoted sentences say what the papers report.
tumor (2 papers, 2021 to 2022). "As mentioned, three genes were mutated exclusively in pre-NACT tumor samples of resistant cases (CSPG4, TUBA3D, SLC35G5)." (PMID 35501919, 2022). "The remaining mutated genes present in pre-NACT tumor samples from resistant cases, TUBA3D and SLC35G5, were the only two genes retained in the post-NACT tumor samples of resistant cases." (PMID 35501919, 2022). "In this study, we have identified a few commonly mutated genes in pre-NACT tumor samples from either sensitive (DNAH5, CYP2D6, NUTM1) or resistant (CSPG4, TUBA3D, SLC35G5) cases, which suggest that these genes could have a potential utility for prediction of the response to NACT." (PMID 35501919, 2022). "We observed nonsilent SNVs or indels in USP8, BSN and SLC35G5 in 1.9, 1.7 and 1.4% of tumours respectively." (PMID 34753926, 2021).
cancer (1 paper, 2025). A tumor composed of atypical neoplastic, often pleomorphic cells that invade other tissues. "The SLC35 gene family, including SLC35G5, has been linked to chemoresistance in various cancers." (PMID 40834150, 2025).
SLC35G5 also shares sentences with these, for which no sentence is quoted: colorectal cancer (1 paper); hepatocellular carcinoma (1); lung carcinoma (1).